ADAM28 (ADAM metallopeptidase domain 28)
Diseases named in the same sentence as ADAM28 in open-access papers (continued):
Sharing a sentence is not in itself a finding about the gene and the disease.
viral infection (1 paper, 2016). "In conclusion, these results showed that the ability of EBNA3C to interact with RBPJ is not only essential for repression in transient reporter assays, but also for the repression of the endogenous COBLL1 and ADAM28-ADAMDEC1 locus in the context of viral infection." (PMID 26751214, 2016). "The primary B cell infection with this virus unequivocally demonstrated that the RBPJ BM EBNA3C virus is completely unable to repress ADAM28, ADAMDEC1 and COBLL1, providing compelling evidence that the EBNA3C:RBPJ interaction is essential in the context of viral infection." (PMID 26751214, 2016).
tumor (22 papers, 2013 to 2025). "For example, ADAM28 expression in tumour epithelium is associated with poor prognosis, but is also important for T cell mobilisation to metastatic lesions." (PMID 35743743, 2022). "We recently reported that ADAM28 depletion in mice causes increased tumour cell dissemination in lungs by decreasing the cancer cytotoxicity mediated by CD8 lymphocytes." (PMID 36685493, 2022). "In experimental tumor cell dissemination models, host ADAM28 deficiency is further associated with a decreased lung infiltration by CD8+ T lymphocytes." (PMID 30647853, 2018). "This exaggerated cancer cell dissemination in ADAM28 deficient animals is associated with a defect in CD8+ T cell trafficking to tumor-bearing organs." (PMID 30647853, 2018). "Previous studies have linked cancer cell-associated ADAM28 expression with tumor progression and metastatic dissemination." (PMID 30647853, 2018). "In the present study, we demonstrate a strong link between host ADAM28 deficiency and tumor cell colonization in lungs." (PMID 30647853, 2018). "This induced tumor cell implantation in ADAM28 deficient lungs was associated with a strong reduction of CD8+ T cell infiltration in lung tissues as compared to wild-type (WT) animals." (PMID 30647853, 2018). "Taken together, these results demonstrate that ADAM28 deficiency in the pulmonary tumor-microenvironment is linked to increased tumor cell colonization in lungs." (PMID 30647853, 2018). "Taken together, they found that ADAM28 is overexpressed in its activated form within human BC tissues by tumor cells and claim that ADAM28 is implicated in cell proliferation via increased bioavailability of IGF-I, which is released from the complex of IGF-I/IGFBP-3 by selective IGFBP-3 cleavage." (PMID 38317965, 2024). "Hence, an altered ability to respond to activating stimuli could explain lower numbers of infiltrating CD8+ T cells observed in spleen and tumor-bearing lungs of ADAM28 deficient mice." (PMID 30647853, 2018). "Moreover, a clear reduction of CD8+ T cell counts could be noticed in ADAM28 deficient lungs once 4T1 tumors were well established in lung tissues (14 days after 4T1 tumor cell injection) (***p<0.001)." (PMID 30647853, 2018). "For B cells, CD20+, CD22+, ADAM28+, and BIRC5 have been identified within tumor‐associated TLSs and are implicated in enhancing the response to ICI therapy." (PMID 41235705, 2025). "ADAM28 appears to be of particular importance in the context of cancer cell biology, since it is highly expressed by tumour cells." (PMID 33571850, 2021). "For example, ADAM28 expression by tumour cells enhances lung metastasis in various cancers including breast and renal cell carcinoma, and its inhibition has been shown to suppress non-small cell lung cancer (NSCLC) metastasis." (PMID 33571850, 2021). "This resistance of VWF-mediated apoptosis was dependent on tumour cell expression of a specific metalloproteinase ADAM28 that cleaves VWF, rendering its apoptotic function inactive." (PMID 33571850, 2021). "Kaplan-Meier analysis revealed that T stage, regional lymph node metastasis, residual tumor, ADAM-10, ADAM-17, and ADAM-28 were associated with shorter time to tumor progression/recurrence (TTP)." (PMID 29776401, 2018). "Higher percentages of Granzyme B and CXCR3 were identified on ADAM28 KO CD8+ T cells isolated from tumor-bearing lungs, which can be correlated to the increased tumor density in ADAM28 KO lungs used for this assay." (PMID 30647853, 2018). "In NSCLC, ADAM28 expression levels correlate with cell proliferation, tumor growth and lymph node metastasis." (PMID 30647853, 2018). "Several in vivo mouse studies demonstrated that specific knockdown of both ADAM28 forms in tumor cells using siRNA or shRNA delays primary tumor growth and lung metastasis of mammary MDA-MB-231 xenografts." (PMID 30647853, 2018).
tumor (continued). "Altogether, these findings strongly suggest that pro-tumor roles should be ascribed to ADAM28 produced by tumor cells and recommend ADAM28 as a promising therapeutic target." (PMID 30647853, 2018). "For this, flow cytometry analyses were performed on whole spleen and lungs derived from C57BL/6JRj WT and ADAM28 deficient mice, intravenously injected with LLC tumor cells (21 days after LLC cell injection), and from C57BL/6JRj tumor-free mice." (PMID 30647853, 2018). "Quantification of haematoxylin-eosin-stained histological lung sections confirmed a significant increase in tumor density in lungs of ADAM28 KO mice (KO+LLC) (*p<0.05)." (PMID 30647853, 2018). "Again, Balb/cJRj ADAM28 KO mice displayed an enhanced tumor density in lungs when compared to corresponding WT littermates (*p<0.05)." (PMID 30647853, 2018). "Altogether, these results demonstrate that cytokines involved in activation and stimulation of CD8+ T cells are commonly produced in an ADAM28-depleted tumor-microenvironment." (PMID 30647853, 2018). "For the first time, we demonstrate a protective role of stromal cell-derived ADAM28 against colonization of tumor cells to lung tissues." (PMID 30647853, 2018). "Of note, tumor-induced MDSC are enriched for multiple ecto-proteases including ADAM28, ADAM9, collagenase-3 (MMP13), stromelysin (MMP3), macrophage elastase, and leukocyte elastase." (PMID 27929373, 2016). "Past research on this gene product in solid (lung) tumors showed that it may act as a tumor suppressor, and that ADAM28 protein levels were higher in adjacent healthy tissues in human colorectal cancer tumors." (PMID 41020821, 2025). "Given that ADAM28 belongs to the ADAM metalloproteinase family that is involved in ECM homeostasis, the depletion of ADAM28+ fibroblasts likely reflects the disruption of stromal integrity and loss of a protective barrier, thereby facilitating tumor invasion." (PMID 41246350, 2025). "However, tumor cells expressing high levels of ADAM28, a novel VWF cleavage protease, displayed resistance to this VWF-induced apoptosis in vivo." (PMID 35327035, 2022). "This is potentially due to the localised, pathological expression of ADAM28 on tumour cells." (PMID 33571850, 2021). "Hence, the downstream reduced infiltration of CD8+ T cells in tumor-bearing ADAM28 KO lungs and the putative consequent reduction of CD8-related anti-tumor activity seem to promote colonization of tumor cells in pulmonary tissues." (PMID 30647853, 2018). "Moreover, CXCR3 levels expressed on CD8+ T cells isolated from tumor-free WT and ADAM28 KO mice and stimulated ex-vivo with IL-2 and IL-7 were similar between both groups." (PMID 30647853, 2018). "In this purpose, lungs of WT and ADAM28 KO mice bearing same sized-tumor islets were analyzed." (PMID 30647853, 2018). "Moreover, lung metastasis induced by an intravenous injection of prostatic PC-9 or MDA-MB-231 cells was decreased when ADAM28 expression was inhibited in tumor cells." (PMID 30647853, 2018). "Taken together, our data show that the observed loss in CD8+ T cell numbers is correlated with ADAM28 deficiency but is not dependent on the mouse strain (C57BL/6JRj or Balb/cJRj) or the tumor cell line used (LLC, B16K1 or 4T1) suggesting a conserved mechanism among different experimental models." (PMID 30647853, 2018). "Moreover, an ex vivo short term cytotoxic assay could demonstrate that CD8+ T cells isolated from ADAM28 KO mice are able to efficiently kill tumor cells." (PMID 30647853, 2018). "The most significant findings included the transcriptional upregulation of MMP1 (125-fold), ADAM28, MMP9, and ADAM9 (5.2-fold, 4.4-fold, and 4.2-fold upregulated) in tumor tissue compared to normal skin." (PMID 38891088, 2024). "This suggests that tumour-expressed ADAM28 inactivates VWF within the circulation, potentially favouring tumour cell survival within the vasculature, thus promoting cancer dissemination." (PMID 33571850, 2021).
tumor (continued). "The expression levels of five genes (ADAM28, BTBD6, CXCL5, PCDH1, and LOC102724689) comprise three rules for the identification of pancreatic-tissue-derived PDX tumor tissues." (PMID 31456818, 2019). "Migration of CD8+ T cells purified from spleens of ADAM28 KO or WT mice was assessed by modified Boyden Chamber assays using CXCL10 at different concentrations, CM from tumor cells or CM from CD8+ T cells used as chemoattractants." (PMID 30647853, 2018). "Proteolytic enzymes such as ADAM28, MMP12 and MMP17, which can enhance extracellular invasion and expansion of tumor volume, were also upregulated in the irradiated SJGBM2-10gy cells." (PMID 30344926, 2018). "Further analysis showed a significant correlation between ADAM-10 overexpression and T stage (P = 0.009) and AJCC TNM stage (P = 0.007), ADAM-17 and larger tumor size (P = 0.007) and AJCC TNM stage (P = 0.002), ADAM-28 and AJCC TNM stage (P = 0.027)." (PMID 29776401, 2018). "A B-cell associated signature distinguished HPV(+) from HPV(−) tumors, and included the DEGs CD200, GGA2, ADAM28, STAG3, SPIB, VCAM1, BCL2 and ICOSLG; the immune signal relative to T-cells was qualitatively similar between TILs of both tumor cohorts." (PMID 27462861, 2016). "In addition, ADAM28 induces the shedding of soluble CD200 in B cells, which delivers immunomodulatory signals to suppress T cell-mediated anti-tumor responses." (PMID 35634306, 2022). "Stimulation of CD8+ T cells with media conditioned (CM) either from LLC, 4T1 or B16K1 tumor cells or from wild-type or from ADAM28 deficient CD8+ T cells induced their proliferation, regardless of ADAM28 production." (PMID 30647853, 2018). "Our innovative data pinpoint a new protective role of host-derived ADAM28 against tumor cell colonization in lungs, specifically by its effects on cytotoxic CD8+ T cell mobilization to lungs bearing metastatic tumor islets, where CD8+ T cells are supposed to exert anti-tumor functions." (PMID 30647853, 2018). "As ADAM28 is described to be expressed by thymic epithelial cells and as CD8+ T cells are the main effectors in tumor immunity, the migration profiles of differentiated CD8+ T cells from the thymus to their secondary activation sites (spleen and lungs) were investigated." (PMID 30647853, 2018). "The result exhibited a more pronounced ADAM28 protein in non-tumor tissues, as compared to the matched tumor tissues." (PMID 27661126, 2016). "Interestingly, tumor cells themselves are not affected by the depletion of host-derived ADAM28 since their proliferation and apoptosis rates were found to be similar in lungs of ADAM28 KO and WT animals." (PMID 30647853, 2018). "Importantly, LLC, B16K1 and 4T1 tumor cells used in this study did not express ADAM28 mRNA, suggesting that only ADAM28 expressed by host non-tumoral tissues impacts tumor cell implantation to lungs." (PMID 30647853, 2018). "In the present study, lower levels of ADAM28 transcript and protein were observed in the CRC tumor tissues relative the matched adjacent non-tumor tissues as examined in terms of respective qRT-PCR assay and IHC staining analysis." (PMID 27661126, 2016). "In the CRC, the correlation of ADAM28 and CRC tumorigenesis has not yet been established, although transcripts of ADAM28 and IGFBP-3 genes in fresh CRC tumor specimens were primary examined in CRC patients with overweight or obese using a microarray analysis." (PMID 27661126, 2016).
cancer (18 papers, 2012 to 2025). A tumor composed of atypical neoplastic, often pleomorphic cells that invade other tissues. "CD20+CD22+ADAM28+ BIR cells were present in cancer-associated TLS and promoted the response to ICI therapy." (PMID 35634306, 2022). "In our model, the TMEM232 expression pattern was similar to ADAM28, with higher expression in low-risk cancers." (PMID 35806060, 2022). "Altogether, our results highlight the crucial importance of ADAM28 expressed by the stromal compartment in the control of cancer dissemination and demonstrate that ADAM28 deficiency decreases CD8+ T cell numbers." (PMID 30647853, 2018). "However, the role of ADAM28 expression is implicated in cancer metastasis." (PMID 33571850, 2021). "Lastly, the ADAM28 gene, which was identified by our machine learning approach to predict mechanistic markers, has been shown in various cancers." (PMID 41020821, 2025). "ADAM28 protease supports cancer cell proliferation, survival and migration as well as metastatic progression." (PMID 35565436, 2022). "At the opposite, ADAM28 was recently proposed to play a protective role against the dissemination of cancer cells by promoting the T cell immune response." (PMID 33805340, 2021). "Considering the importance of ADAM-10, ADAM-17, and ADAM-28 in cancer progression, we detected their expression in HC by immunohistochemistry." (PMID 29776401, 2018). "Previous reports, focusing on cancer cell-derived ADAM28, have demonstrated that ADAM28 promotes cancer development and progression." (PMID 30647853, 2018). "In contrast, a knockdown of ADAM28 in CRC cells by shRNA showed an enhanced capacity of cancer cell proliferation and migration in vitro." (PMID 27661126, 2016). "Results from this study suggest that miR-552 acts as an oncogene in CRC, which can promotes cancer metastasis through a mechanism in part by directly targeting ADAM28 in CRC." (PMID 27661126, 2016). "In a study of the human tissue microenvironment in non-small cell lung cancer demonstrated that the disintegrin and metalloproteinase 28 (ADAM28) can promote metastasis by binding to and cleaving vWF in carcinoma cells." (PMID 25886574, 2015). "The overexpression of ADAM8, ADAM9, ADAM10, ADAM12, ADAM15, ADAM17, and ADAM28 are reported from various cancers." (PMID 22272227, 2012). "Some of them require more detailed studies since their biological role, especially in cancer, is unknown, or the data are contradictory (ADAM28, TMEM232, DPY19L3-DT, and E9PMD0)." (PMID 35806060, 2022). "In addition, oncoprotein v-src also showed an ability to induce ADAM28 expression in human carcinoma cell lines of the lung, breast, ovary, kidney and colon." (PMID 27661126, 2016). "However, certain aggressive cancer cells are able to escape vWF-induced cell death through production of the protease ADAM28 that can counterbalance the pro-apoptotic function of vWF." (PMID 26306290, 2015). "Moreover, ADAM28 deficiency has been associated with impaired CD8+ T recruitment in lung and spleen contributing to a protective role for host ADAM28 against metastasis dissemination of cancer cells." (PMID 36685493, 2022). "Hence, combined with the results of PRECOG and survival analysis, it implied that the high expressions of CD20, CD22, CD79B, and ADAM28 might predict a positive response to anti-PD-1 immunotherapy for pan-cancer patients." (PMID 35634306, 2022). "In addition, the distinct biofunctions of ADAM28 observed in various cancer types may imply a cancer type context-dependent biological function of ADAM28 in CRC cells, which warrants further investigations." (PMID 27661126, 2016). "Some genes consistently indicated a positive prognosis in different cancer types, such as CD20, ADAM28, MEF2C, CPNE5, and ATP2A3." (PMID 35634306, 2022). "However, the role of host-derived ADAM28 in cancer dissemination processes remains unclear." (PMID 30647853, 2018).
cancer (continued). "ADAM28 may play a key role in cancer cell proliferation and metastasis, whereas ADAM17 is a target of tumorigenesis, but the role of ADAM15 in cancer biology remains to be elucidated." (PMID 35565436, 2022). "The non-cancerous bile ducts showed negative or weak staining for ADAM-10, ADAM-17, and ADAM-28, whereas most cancer cells showed strong staining for these three proteins." (PMID 29776401, 2018).
infection (2 papers, 2016). The state of being infected such as from the introduction of a foreign agent such as serum, vaccine, antigenic substance or organism. "The LOVO and LS174T CRC cells that co-infected with LV-shADAM28-972 vector and LV-miR-552-inh were employed for the study of loss-function of ADAM28, as an infection of LV-miR-552-inh resulted in an elevated ADAM28 expression in LOVO and LS174T cells." (PMID 27661126, 2016). "In order to determine whether binding of EBNA3C to RBPJ is necessary for the repression of the endogenous COBLL1 and ADAM28-ADAMDEC1 locus in the context of infection, a new EBV recombinant encoding the RBPJ binding mutant of EBNA3C (RBPJ BM EBNA3C) was constructed." (PMID 26751214, 2016). "Consistent with the results of the luciferase reporter assays and the ChIP studies, infection with the RBPJ BM EBNA3C virus was unable to repress ADAM28, ADAMDEC1 or COBLL1." (PMID 26751214, 2016). "Infections with wild type, Rev and EBNA3B KO viruses resulted in a reduction of both ADAM28 (2–3 log fold) and ADAMDEC1 (1–2 log fold) levels of mRNA, over a period of 30 days after infection." (PMID 26751214, 2016). "Finally, in order to determine whether binding of EBNA3C to RBPJ was necessary for the repression of the endogenous COBLL1 and ADAM28-ADAMDEC1 locus, RNA samples taken every 5 days from the time of infection of primary B cells with the recombinant RBPJ BM EBNA3C virus were analysed." (PMID 26751214, 2016).
ADAM28 also shares sentences with these, for which no sentence is quoted: adenoma (1 paper); astrocytic tumor (1); B-cell acute lymphoblastic leukaemia (1); B-cell acute lymphoblastic leukemia (1); bladder transitional cell carcinoma (1); brain tumor (1); COVID-19 (1); dementia (1); head and neck squamous cell carcinoma (1); liver fibrosis (1); lymphoma (1); nasopharyngeal carcinoma (1); oral squamous cell carcinoma (1); renal cell carcinoma (1); renal clear cell cancer (1); sarcoma (1); skin squamous cell carcinoma (1); triple-negative breast carcinoma (1).